BRD4 (bromodomain containing 4)
Diseases named in the same sentence as BRD4 in open-access papers (continued):
Sharing a sentence is not in itself a finding about the gene and the disease.
cancer (continued). "BRD4 is expressed in various cells, including cancer cells and immune cells, and previous investigations on the BRD4 inhibitor focused on its direct effects on cancer cells." (PMID 37685868, 2023). "A variety of studies have suggested that BRD4 modification is correlated to cancer progression and metastasis." (PMID 37737256, 2023). "Taken together, BRD4 is a well-documented factor promoting cancer stemness across distinct types of solid tumors, and direct targeting of BRD4 significantly attenuates the cancer stem cell-like properties of tumors." (PMID 36674511, 2023). "Dysregulation of BRD4 has been involved in a variety of cancers including hematological and several solid malignancies." (PMID 36733715, 2023). "It was reported to activate the transcription of bromodomain protein 4 (Brd4), which played a critical role in development, cancer progression, and virus‐host pathogenesis." (PMID 37485815, 2023). "Bromodomain-containing Protein 4 (BRD4) is a transcriptional regulator which coordinates gene expression programs controlling cancer biology, inflammation, and fibrosis." (PMID 37435059, 2023). "As BRD4 inhibitors induce cancer cell death by promoting stalling of Pol II, their mechanism of action also promotes the subsequent annealing of the transcribed pre-mRNA strand to its template, hence forming R-loops." (PMID 37108225, 2023). "JQ1 inhibited the expression of an HMT named G9a, reduced H3K4me3 abundance at BRD4, and further induced ferroptosis in cancer cells." (PMID 37229485, 2023). "In summary, we provide a theoretical basis for the inhibition mechanism of ZL0590 against BRD4, which can be used as a reference for improving the development of drug targets for cancer therapy." (PMID 37446009, 2023). "Bromodomain and extracellular terminal (BET) family (including BRD2, BRD3, and BRD4) is considered to be a major driver of cancer cell growth and a new target for cancer therapy." (PMID 36793283, 2023). "BRD4 has received considerable attention as a cancer therapy target because several cancers depend on BRD4-mediated c-myc, fos, and aurora kinase B expression." (PMID 36991452, 2023). "These inhibitors disrupt the interaction between BRD4 and actylated histones and have been used in pre-clinical and clinical trials against various cancer entities." (PMID 38201534, 2023). "Targeting BRD4 in cancer therapy has gained attention due to its role in transcriptional regulation." (PMID 38201534, 2023). "BRD4 has been found to be upregulated in many cancers to modulate oncogenic activities and cancer cell malignancy." (PMID 37509171, 2023). "Structurally, diverse cores of BRD4 inhibitors have exhibited potent anticancer activity against various types of cancers in both preclinical studies and clinical trials." (PMID 37765111, 2023). "As BRD4 plays an important role in mediating the expression of genes involved in cancers and non-cancer diseases, several drugs targeting it are currently in clinical trials." (PMID 37628760, 2023). "The mRNA expression levels of BRD4 was more significantly increased in GBM patients than other types of cancer." (PMID 36711038, 2023). "Meanwhile, Astex Pharmaceuticals has reported the successful application of 2 drug precursors to degrade 2 cancer targets, bromine domain protein 4 (BRD4) and ERK1/2, utilizing IEDDA click chemistry to form a hetero-bifunctional molecule in cells." (PMID 38107023, 2023). "For example, the BETi JQ1 and BET degrader dBET6 can target the transcription elongation regulator BRD2 and BRD4 bromodomain, resulting in aberrant R-loop accumulation as well as DNA damage and cell death in cancer cells." (PMID 36750826, 2023). "The galactose on liposome surfaces was intended to specifically bind asialoglycoprotein receptors (ASGPRs) on cancer cells, and BRD4-degrading ARV-825 was loaded in the bilayer of liposomes to produce GALARV." (PMID 36839734, 2023).
cancer (continued). "Furthermore, MED12 and BRD4 could cooperate to sustain cancer growth upon loss of mediator kinase." (PMID 37488513, 2023). "Inhibiting BRD4 has been proven to be effective in treating malignant tumors with pathological activation of c-MYC." (PMID 37446009, 2023). "It has been shown that BRD4 regulates splicing of multiple genes in normal and cancer cells by interacting directly with the splicing machinery." (PMID 37705995, 2023). "To address that, we searched for correlations of GDF15 and BRD4 linear regression slopes upon treatment in NCI-60 cancer cell lines." (PMID 37495707, 2023). "The expression levels of BRD3 and BRD4 were significantly upregulated in ACC patients at different cancer stages." (PMID 36793283, 2023). "Taken together, these results suggest that increased acetylation of the PD-L1 gene by classical zinc-dependent HDACi and BRD4, which reads acetylated sites, contributes to the upregulation of PD-L1 on the cancer cell surface." (PMID 37603071, 2023). "The inhibition of BRD4 shortens the communication between SE and the target gene promoter, and then leads to the specific inhibition of oncogenes and cell death in cancer cells." (PMID 37446009, 2023). "Given the strong correlation and cross-regulation between BRD4 and Myc, BETis are effective against Myc-driven cancers; indeed, Myc is also used as a readout to predict tumour responsiveness to BETis." (PMID 36902175, 2023). "The PEG-PLGA nanoparticles gradually released ARV-825 inside the cancer cells, inducing BRD4 degradation and subsequent inhibition of undruggable c-Myc transcription." (PMID 36839734, 2023). "Due to its role in the formation of SEs and control of oncogene expression, BRD4 is a well-established factor in cancer cells." (PMID 37501079, 2023). "BRD4, an epigenetic and transcriptional regulator, plays a critical role in early embryonic development, tumorigenesis, and cancer progression." (PMID 37737256, 2023). "In the field of cancer therapy, inhibitors of SE complex proteins, such as BRD4, CDK7, or CDK9, show great potential." (PMID 37501079, 2023). "BET inhibitors specifically disrupt the binding activity of BRD4, one of the SE complex components, decreasing the production of SE-driven oncogenes and attenuating cancer cell proliferation." (PMID 37501079, 2023). "BRD4 is significantly upregulated in a number of cancer types, including melanoma, colon, breast, and bladder cancers." (PMID 36674511, 2023). "Since we found that Ovcar4 cells overexpressing BRD4 isoforms are particularly sensitive to paclitaxel, we then investigated if combination of paclitaxel and other anti-cancer compounds can enhance the antitumor effect even further." (PMID 37705995, 2023). "In cancer, especially regarding cancer stemness, the involvement of BRD4 was most extensively studied." (PMID 36674511, 2023). "With the increased understanding of tumor types that are regulated by BET/Brd4-associated oncogenes and those driven by the Brd4 fusion, there has been enormous interest in developing novel BET inhibitors for cancer treatment." (PMID 37049806, 2023). "The overexpression of BRD4 has been demonstrated in various kinds of cancer, such as breast, lung, prostate, and hematological malignancies." (PMID 37765111, 2023). "NHWD-870, a known Brd4 inhibitor with anti-cancer properties, exhibits additional attributes such as antioxidant, anti-inflammatory, and anti-apoptotic effects, suggesting its potential to preserve renal tissue and mitigate damage during ischemic insults." (PMID 37675155, 2023). "We used the Genomics of Drug Sensitivity in Cancer database to evaluate the inhibitory effect of BRD4-targeted drug PFI-1 and (BRD2, BRD3, and BRD4)-targeted drug I-BET-151 on ACC cell lines." (PMID 36793283, 2023). "On the other hand, among the four BET family of proteins, Brd4 has been the most extensively studied, whereas the relative role of Brd2/Brd3 in cancer cell survival still remain elusive." (PMID 37049806, 2023).
cancer (continued). "Blockade of the BRD4 interaction with HATs by small molecule inhibitors has been shown to effectively block cell proliferation in cancers, some of which have, in fact, been evaluated in human clinical trials." (PMID 37444447, 2023). "BRD4, a protein featuring bromodomains that selectively recognize acetylated histones, is frequently found to be overexpressed in cancer." (PMID 38201534, 2023). "Following IFN-γ stimulation, BRD4 is rapidly recruited to the PD-L1 locus, accompanied by increased H3K27ac and RNA Polymerase II (RNA Pol II) occupancy in cancer cells." (PMID 37764768, 2023). "Among the four BET proteins, Brd4 is known to be highly enriched in super-enhancers that promote the expression of factors including c-MYC to support cancer growth and development." (PMID 37049806, 2023). "Significant inhibition of BRD4 resulted in the depletion of YAP1 and loss of cancer stem cell-like properties." (PMID 36674511, 2023). "Given that BRD4 was shown to be upregulated in HGSOC cancer cell lines, it is important to note that, in recent years, BRD4 has emerged as a potential target for cancer therapy." (PMID 38201534, 2023). "BRD4 inhibition also suppresses cancer stem cell properties and decreases respective aldehyde dehydrogenase 1 (ALDH1) + marked stem cells in radiation‐resistant EAC cells." (PMID 37994501, 2023). "Brd4 has attracted enormous attention as a promising molecular target for cancer therapy in recent years because pharmacological inactivation of Brd4 was shown to remarkably suppress expression of the MYC oncogene." (PMID 37049806, 2023). "As such, BD1 is essential for disrupting BRD4 interactions and is a promising target for cancer treatment." (PMID 37570684, 2023). "The main function of BRD4 in these cancers is acting as a positive regulator of transcription of target genes." (PMID 37689115, 2023). "BD1 is critical for BRD4 to recognize the acetylation moiety on histones and participates in transcription control of cancer-related genes." (PMID 36274096, 2022). "Bromodomain-containing protein 4 (Brd4) mediates the expression of genes involved in several human pathologies such as cancers, inflammatory diseases and acute heart failure." (PMID 35887019, 2022). "This increase in pro-proliferative c-myc targets is clearly a driver of cancer as genetic inactivation of c-myc or use of Brd4 inhibitors, which also reduce c-myc levels, has significant antitumor activities." (PMID 35438057, 2022). "Among these, LINC00824 (PVT1), which is adjacent to c-MYC gene and frequently upregulated in many cancers, was identified as a BRD4 target." (PMID 35399501, 2022). "BRD4 is recruited to SEs and consequently functions as an epigenetic reader to promote the transcription of SE-marked genes in cancer cells." (PMID 35159127, 2022). "We found that 2n lacked anti-proliferative effects, indicating that the cyclopropenone structure plays an essential role in inhibiting BRD4 functions through perturbing phase separation, thereby suppressing cancer cell growth." (PMID 35159127, 2022). "In conclusion, we found IRF1 to be a general predictor for CD274 expression in all three studied cancer types, and STAT1, NFKB, HIF1A and BRD4 to be predictors for some of these cancer types." (PMID 35289334, 2022). "In human cancer cells, histone hyperacetylation driven by a fusion oncoprotein (BRD4-NUT) facilitates the formation of a newly recognized chromatin interaction with a unique sub-compartment." (PMID 36358822, 2022). "We conclude that BRD4 and SWI/SNF chromatin remodelling complexes emerge as interesting future drug targets in FET‐FOP‐caused cancers as well as in other cancer types with aberrant SWI/SNF function." (PMID 35182012, 2022).
cancer (continued). "Disease-specific elevation of nucleoporin, a component of the nuclear pore complex (NPC), is a determinant of cancer malignancy, but BRD4-driven changes of NPC composition remain poorly understood." (PMID 35159127, 2022). "Various lines of evidence have suggested that BRD4 facilitates malignant phenotypes in diverse cancer contexts." (PMID 35159127, 2022). "We assessed BRD4 expression in cancer and the correlation between BRD4 mRNA expression and prognosis using public databases." (PMID 36224471, 2022). "For example, Brd4 is found to be overexpressed in many kinds of cancers and is involved in the initiation and progression of cancer by providing survival signals to cancer cells." (PMID 36539410, 2022). "Up till now, about 20 BRD4 inhibitors have been entered into clinical trials, some of which showed valuable therapeutics for several cancers, including hematological malignancies and non-small cell lung cancer." (PMID 36387198, 2022). "BRD4, acting as a histone acetyl-reader, is an important regulator of chromatin structure, which plays a role in cancer progression, cell proliferation, DNA damage, and gene regulation." (PMID 35765893, 2022). "In conclusion, our findings highlighted an aminocyclopropenone compound as a novel therapeutic drug blocking BRD4 assembly, thereby preventing BRD4-driven oncogenic functions in cancer cells." (PMID 35159127, 2022). "This raises the question of the selectivity and efficacy of BRD4 inhibitors in targeting YAP-dependent transcriptional addiction in cancer cells." (PMID 35871292, 2022). "Multiple studies have demonstrated that combined BRD4 and MEK inhibition is beneficial, especially in KRAS/NRAS-driven or NF1-deficient cancer, including TNBC." (PMID 36139513, 2022). "The study using NHWD870 in treating cancer has shed some light on the general mechanism of how inhibition of BRD4 affects the regulation and interaction of gene expression." (PMID 36239350, 2022). "BET proteins are dysregulated in inflammation, cancer, metabolic disorders, neurodegenerative disorders, renal diseases, lung diseases, etc.; the most studied protein in a pathological sense is BRD4." (PMID 35401196, 2022). "Ferroptosis can be induced under JQ1 treatment and Brd4 knockdown in various cancer cell lines and mouse tumor xenografts." (PMID 36539410, 2022). "Inhibition of BRD4 has also been shown to restore anticancer immunity by reducing PD-L1 expression on cancer cells." (PMID 35918330, 2022). "In cancer development, BRD4 linkage to NF-κB prevents RELA ubiquitylation, which then blocks RELA degradation through proteasome." (PMID 35401196, 2022). "Further studies have shown that the combined inhibition of CDK1 and BRD4 can overcome the resistance of cancer to BETis to more effectively kill cancer cells related to BRD4-dependent survival." (PMID 35402244, 2022). "PHD2 was significantly overexpressed in AML patients, which shows that PHD2-mediated proline hydroxylation is a potential oncogenic pathway in AML, driving BRD4-mediated gene expression and cancer cell proliferation." (PMID 35402244, 2022). "Several reports have shown that BRD4 expression was significantly upregulated in different kinds of tumors, and BRD4 played vital role in the progression of cancers." (PMID 35371325, 2022). "BRD4 is upregulated in diverse types of cancer, resulting in the induction of potent oncogenes such as MYC, c-MYB, ERG, and E2F1." (PMID 35399501, 2022). "GNE987 and MZ1 disrupted the binding of BRD4 to acetylated chromatin, thereby inhibiting cancer growth and inducing apoptosis." (PMID 36114560, 2022). "BRD4 is an important regulator of gene expression and remains a prominent transcriptional vulnerability in human cancer." (PMID 35337136, 2022). "The Bromodomain and extra-Terminal Domain (BET) protein BRD4 was a transcriptional and epigenetic regulator that plays a key role in embryonic and cancer development." (PMID 36524001, 2022).
cancer (continued). "As c-Myc is critical for the metabolic demands of cancer cells, we tested the impact of BRD4 degradation on oxidative phosphorylation and observed a reduction in oxidative phosphorylation." (PMID 35173274, 2022). "The SMIs designed for the treatment of cancer include, for example, BRD4 inhibitor (JQ1) and CDK7 inhibitor (THZ1)." (PMID 36010973, 2022). "The inhibitor of BRD4 has great promise for cancer therapy, it competes with acetylated residues to bind to the BRD4 bromodomain, thereby reducing RNA-PolII flux and blocking transcription of key oncogenes." (PMID 35252174, 2022). "In this study, we demonstrated that molibresib-mediated inhibition of BRD4 strongly promoted pexophagy in cancer cells." (PMID 36139416, 2022). "By doing so, BRD4 regulates the expression of genes that govern cell growth and evasion of apoptosis in cancer (e.g., MYC, BCL6, BCL2, and CDK4/6)." (PMID 35743155, 2022). "BRD4 inhibition has been demonstrated to directly improve anti-cancer (CAR) CD4+ and CD8+ T cell activity, for example by inducing cytotoxicity and reducing T cell exhaustion." (PMID 36139513, 2022). "BRD4 is the most cancer-related BET family member and plays a pivotal role in certain types of cancer." (PMID 35601153, 2022). "Mechanismly, BET inhibitors exert their anti-tumor effect mainly through the inhibition of MYC, a downstream gene of BRD4, in many cancer types." (PMID 36187481, 2022). "Our data confirm the role of YAP in promoting the recruitment of RNApol2 in a BRD4-dependent way and its role in controlling elongation in cancer cells." (PMID 35871292, 2022). "Here, we developed novel aminocyclopropenones and investigated their biological effects on cancer cell growth and BRD4 functions." (PMID 35159127, 2022). "This work proposes a novel approach for specifically delivering the BRD4 degrader to regress cancers." (PMID 35988145, 2022). "Currently, the SE-related components recognized as cancer therapeutic targets are bromodomain containing 4 (BRD4), cyclin dependent kinase 7 (CDK7), E1A binding protein P300 (EP300), CDK8 and CDK19." (PMID 35303940, 2022). "In this study, we also demonstrated that preventing BRD4 functions reduced not only the excessive growth capacity of cancer cells but also the size of their nucleus." (PMID 35159127, 2022). "A paired-comparison test of data from TCGA showed that BRD4 expression was higher in EC cancer tissues than in corresponding adjacent tissues." (PMID 35902869, 2022). "The cancer-specific susceptibility to BET inhibition has been explained by the acquisition of super-enhancers during tumorigenesis and a preferential loss of BRD4 from the mediator complex at super-enhancers upon treatment with BET inhibitors." (PMID 35681734, 2022). "Blockage of BRD4 reduced the growth of GC in vitro, which supporting the tumor-promoting role of BRD4 in this type of cancer." (PMID 36352160, 2022). "Brd4 inhibition promotes apoptosis of cancer cells and has exhibited promising therapeutic effects in cancer treatment." (PMID 36539410, 2022). "Since the SL effects existed between CHK1i and ATRi, it is understandable that BRD4 inhibition synergized with ceralasertib in killing a number of cancer cell lines." (PMID 35458687, 2022). "Given the prevalence of super-enhancer dysregulation in cancer, inhibition of super-enhancer-driven gene expression has become a popular therapeutic strategy, with drugs targeting BRD4 and CDK7 being developed for anticancer therapies." (PMID 35563864, 2022). "We found that in CCLE (Cancer Cell Line Encyclopedia) samples, BRD4 was the top gene in AML cell lines compared to other types of cancer cell lines." (PMID 35958877, 2022). "Together, our results suggest that BRD4-driven NUP210 regulates cancer cell growth and nuclear architecture." (PMID 35159127, 2022).